CCR4 (C-C motif chemokine receptor 4)
Diseases named in the same sentence as CCR4 in open-access papers (continued):
Sharing a sentence is not in itself a finding about the gene and the disease.
infection (continued). "A negative correlation confirmed that as more CD4+ cells, lesser CD4+Foxp3+ cells in the lungs of CCR4−/− mice, but not WT mice, at 70 days of infection." (PMID 30584243, 2018). "Because the absence of CCR4 increased the number of CD4+ cells in the lungs in the chronic phase of infection, we further evaluated the functional activity of CD4+ subsets." (PMID 30584243, 2018). "This study adds novel information on other potential homing biomarkers such as CCR4, showing that in combination with CD27 (CD27−CCR4+IFN-γ+CD4+ T-cells) could be a phenotype to discriminate between disease and infection." (PMID 30687314, 2018). "MIP-1α signals through CCR1, CCR4, and CCR5 and MIP-1β signals directly through the CCR5, suggesting that pregnancy may induce different pathways signaling in response to infection." (PMID 29176767, 2017). "Expression of the type 2 chemokine ligands, CCL17 and CCL22 increased as early as 7 days post-infection and remained upregulated up to 21 days of infection, but somewhat surprisingly their receptor, CCR4, was not." (PMID 28103263, 2017). "In contrast to the reported properties of peripheral blood derived Th22 cells without a characterised antigen specificity, IL-22 production in response to PA infection was from memory CD4+ T cells that did not express the skin-homing receptors CCR4 or CCR10." (PMID 24587305, 2014). "In other hand, both Tc1-related CCR5 and Tc2-related CCR4 among CD8 T cells showed an increase in CD107a expression and in effector/migratory markers as CD29, CD44HIGH and CD127LOW respectively, indicating their potential function during acute DENV-infection." (PMID 22815692, 2012). "Taken together, the key insights from these analyses between adults and children underscore the absence of severe infection in children cases, as evidenced by the lack of CCR4+ CD8+ T cells, in conjunction with variations in CD56 expression in the exhausted NK cell phenotype." (PMID 38429462, 2024). "Though this data indicates these pathways are not important in this context, their dysregulation and regulation of MHC could, however, contribute to CCR4‐NOT regulation of HCMV in a natural human infection." (PMID 37846490, 2023). "We next asked whether regulation of infection by CCR4‐NOT complex components was restricted to HCMV or extended to other DNA viruses." (PMID 37846490, 2023). "Furthermore, many chemokine receptors like CCR4, CCL14, XCR1 along with the adaptor molecules CRKII and ELMO1 were downregulated during initial and mid stages of infection, and in contrast, some G protein signaling molecules such as GNAI, GNB1, FAK and FAK2 were upregulated in infected fish." (PMID 33177569, 2020). "In the present work, we have shown that intraperitoneal infection of mice with CVB5 induced pancreatic duct cells to produce the chemokine CCL17, whereas the expression of its receptor, CCR4, was increased in the pancreas, and CCR4+ cells accumulated in the PLN." (PMID 31611578, 2019). "Our data reveal a previously unknown mechanism by which cells important for the resolution of infection are able to migrate to the site and perform their functions, and our data point to CCL17 and CCR4 as potential targets for the treatment of viral pancreatitis." (PMID 31611578, 2019). "Although CCR4−/− mice survived the infection (data not shown), their pancreata were more injured than WT mice, presenting significantly more inflammatory infiltrates, edema and necrosis on days 3 and 7 post-infection." (PMID 31611578, 2019). "A decrease in the frequency of CD4+Foxp3+ cells was found in the lungs of infected CCR4−/− mice at 15 and 70 days of infection compared with their WT counterparts, and the number of CD4+Foxp3+ cells was significantly lower in CCR4−/− mice at 70 days of infection compared with WT mice." (PMID 30584243, 2018). "Notably, while CCR4 was mostly absent on the surface of mock NK cells, we observed a substantial increase in CCR4 expression driven by infection with VZV." (PMID 29709039, 2018).
infection (continued). "The absence of CCR4 causes an imbalance in lung CD4+ and CD4+Foxp3+ cells, which exacerbates the Th1-mediated immune response, induces excessive pulmonary inflammation and progression of infection." (PMID 30584243, 2018). "In contrast, HIV-specific CD8+ T-cells express low levels of CCR6 and CCR4 and thus may be impaired in their ability to colocalize and control viral replication in CCR6+CCR4+ CD4+ T-cells, such as Th17 cells which are highly permissive to infection." (PMID 22470433, 2012). "Thus, changes in the abundance of this non‐nuclease component may have additional complex effects on mRNA targeting or the deadenylation activity of CCR4‐NOT during infection." (PMID 37846490, 2023). "Additionally, CXCR3 was down regulated and CCR4 up regulated in memory CD4+ Treg exposed to ANDV-GP VLPs, this suggest that ANDV-GP could specifically act over CXCR3 in CD4+ Treg cells potentially altering their ability to migrate to the site of infection." (PMID 32984065, 2020). "However, a recent study demonstrated that CCR4 expression can be induced on infection and HBZ expression, hence it may not be initially expressed on target cells." (PMID 28639618, 2017). "Depletion of CCR4‐NOT components led to a global reduction in viral RNA expression, viral DNA synthesis, and impaired viral protein production late in infection, and selectively impacted host responses." (PMID 37846490, 2023). "Most CD4+ T-cells in the blood, spleen, and MLN of control HIS-NSG mice expressed CC-chemokine receptor 4 (CCR4) without the presence of CCR5 and CXC-chemokine receptor 3 (CXCR3), which were indeed upregulated upon infection." (PMID 34685494, 2021). "At 70 days of infection, lung CFU number declines in C57BL/6 mice, which are resistant to M. tuberculosis infection, but not in CCR4−/− mice." (PMID 30584243, 2018). "We hypothesize that the activity of Ccr4-NOT could be targeted for future antifungal drug discovery, a proposition supported by the fact that inactivation of the genes encoding subunits of Ccr4-NOT in C. albicans and C. neoformans reduces virulence in the mouse infection model." (PMID 24391665, 2013). "Together, these data indicate that the dependence of virus gene expression and replication upon CCR4‐NOT components is not universally shared among DNA or herpes viruses, and the complex is important for lytic infections of both laboratory and clinical strains of HCMV." (PMID 37846490, 2023). "Depleting scaffolding components of the CCR4‐NOT complex selectively reduced accumulation of HCMV RNA and proteins late in infection and impaired viral DNA synthesis, but did not detectably impair replication of HSV‐1, a related herpesvirus subfamily member, or VACV." (PMID 37846490, 2023).
inflammation (5 papers, 2008 to 2024). Aberrant reaction of the microcirculation characterized by movement of fluid and leukocytes from the blood into extravascular tissues. "Conjunctival inflammation in acute forms of ocular allergy has increased CCR4+CCR9+ effector T cells, with a diminished frequency of CD4+CD25+FOXP3+ regulatory T cells in peripheral blood." (PMID 33114004, 2020). "In contrast to these studies, ovalbumin challenged CCR4 null mice were not protected against airways inflammation compared with littermates, nor were ovalbumin challenged guinea pigs protected from lung inflammation when CCR4 was neutralized by an antibody." (PMID 25981299, 2015). "Because CCR4 induces the recruitment of regulatory T cells to the lung, we used CCR4-deficient (CCR4−/−) mice as a tool to address the role of CD4+Foxp3+ T cells in the chronic lung inflammation induced during M. tuberculosis infection." (PMID 30584243, 2018).
metabolic disorders (5 papers, 2022 to 2025). "For instance, CNOT1, a component of the CCR4-NOT complex, is known to regulate mRNA stability and translation, processes that could be dysregulated in metabolic disorders." (PMID 40740938, 2025).
hematological malignancies (3 papers, 2015 to 2024). "Currently, clinically approved drugs targeting chemokines include anti-CCR4 antibodies (Mogamulizumab) and CXCR4 antagonists (Plerixafor, AMD3100), which are utilized in the treatment of hematological malignancies." (PMID 39691368, 2024). "Of particular interest is the new T cell therapy for solid tumors, similar to the Car-T in hematological malignancies, which could be used in small dysplastic lesions of the larynx, especially when CCL20 and CCR4 are the most important gene alterations observed in dysplasia." (PMID 39273632, 2024).
renal disease (3 papers, 2005 to 2024). "The therapeutic impact of the blockade of CCR1, CCR2, CCR4, CCR5, or the corresponding ligands has been further studied in various renal disease models." (PMID 16200331, 2005). "This tissue specificity in T-cell mediated CCL5 to CCR4 interactions was not attributable to the composition of niche cell types in the skin, as T cells were also present in lung, colon and kidney disease interactions." (PMID 40809141, 2024).
bacterial infection (2 papers, 2014 to 2024). "Thymus and activation-regulated chemokine (TARC) selectively recruits CCR4-expressing T cells and functions in the pathogenesis of lethal liver damage from bacterial infection." (PMID 38715085, 2024).
heart disease (2 papers, 2020 to 2024). "The CCR4-NOT complex has previously been implicated in heart disease; we have demonstrated that silencing of genes Ubc4 and Not3 cause cardiac dilation and dysfunction in Drosophila." (PMID 32471864, 2020). "The combined use of GWAS studies and cardiac model systems in this study has enabled us to connect CNOT1, CNOT7 and, overall, CCR4-NOT complex function to cellular and whole-heart phenotypes in the context of human heart disease." (PMID 32471864, 2020).
liver (2 papers, 2016 to 2021). "Compared to control cells, overexpression of CCR4 in SW1116 cells increased liver metastases dramatically (Vector group: 4.00 ± 1.91, CCR4 group: 9.43 ± 2.23)." (PMID 27356745, 2016).
blood cancers (1 paper, 2025). "Examples of afucosylated antibodies include mogamulizumab (anti-CCR4 antibody), which has shown superior efficacy in clinical trials and is now approved for the treatment of certain blood cancers." (PMID 40469310, 2025).
CNS tumor (1 paper, 2015). "An increased ratio of CCR4+FoxP3+ Tregs to total CD4+ T cells correlates with impairment of CD4+ T cell proliferation in peripheral blood specimens obtained from CNS tumor patients." (PMID 26528477, 2015).
head and neck tumors (1 paper, 2024). "CCR4 was reported to be over-expressed in many hematological and solid tumors and also in head and neck tumors." (PMID 39273632, 2024).
hematological cancers (1 paper, 2018). "To date, afucosylated anti-CD20 and anti-CCR4 mAbs have been approved against hematological cancers and preclinical studies of afucosylated mAbs against solid tumors have also shown promising results." (PMID 29568351, 2018).
respiratory diseases (1 paper, 2024). "Furthermore, CC motif chemokine ligand 17 stimulates the release of greater amounts of CGRP than other inflammatory cytokines through a CCR4-dependent mechanism that has been implicated in other respiratory diseases." (PMID 38792587, 2024).
CCR4 also shares sentences with these, for which no sentence is quoted: Allergy (10 papers); lymphopenia (5); B cell lymphoma (3); idiopathic pulmonary fibrosis (3); tropical spastic paraparesis (3); allergic contact dermatitis (2); Arrhythmia (2); Co-infection (2); cutaneous melanoma (2); high-grade glioma (2); Hypercalcemia (2); Insulin resistance (2); malaria (2); metastasis (2); pancreatic ductal adenocarcinoma (2); pulmonary sarcoidosis (2); respiratory infection (2); squamous cell carcinoma (2); acute GVHD (1); acute liver failure (1); acute respiratory distress syndrome (1); airway allergy (1); allergic conjunctivitis (1); alopecia (1); anorexia nervosa (1); Arthralgia (1); astrocytoma (1); benign tumors (1); Cachexia (1); cardiovascular diseases (1).
A further 63 diseases each share a sentence with CCR4 in 1 paper.